MMP9 (matrix metallopeptidase 9)
Diseases named in the same sentence as MMP9 in open-access papers (continued):
Sharing a sentence is not in itself a finding about the gene and the disease.
breast carcinoma (continued). "In fact, a recent paper showed that ST6Gal-II downregulation inhibited cancer progression, cell adhesion and invasion, and suppressed ICAM-1, VCAM-1, CD24, MMP2, MMP9, and CXCR4 expression in breast cancer cells." (PMID 34577144, 2021). "Calycosin treatment inhibited epithelial-mesenchymal transition (EMT) of breast cancer cells by significantly increasing E-cadherin levels and decreasing N-cadherin, Vimentin, CD147, MMP-2, and MMP-9 levels through downregulation of BATF and TGFβ1." (PMID 34096887, 2021). "LOX, MMP2, MMP3, MMP9, RHOA, VIM gene panel expression monitoring was considered because they are correlated with a more aggressive and invasive phenotype in breast cancer cells." (PMID 33543395, 2021). "Calycosin in a higher dose significantly reduced the expression levels of the forkhead box P3 (Foxp3), followed by downregulation of VEGF and MMP-9 in MCF-7 and T47D breast cancer cells." (PMID 34462889, 2021). "This information at least provides an insight about the significance of MMP-9 in TNBC and HER2-enriched human breast cancer." (PMID 34181339, 2021). "Recently, Mor hydrate was studied in the metastasis of MCF-7 human breast cancer cells, where Mor hydrate suppressed 12-O-tetradecanoylphorbol-13-acetate (TPA)-induced cell migration and invasion via the inhibition of MMP-9 mRNA and protein expression." (PMID 33498927, 2021). "Among the MMPs, MMP-2 and MMP-9 are strongly correlated with tumor invasion and metastasis in breast cancers, as MMP-2 is more constitutively expressed in metastatic cancers and MMP-9 is highly inducible by various stimuli." (PMID 34483918, 2021). "It was suggested that the statin inhibited invasion and metastasis in the aggressive breast cancer cell line via blockage of the mevalonate pathway and inhibition of both MMP-2 and MMP-9." (PMID 33906301, 2021). "In conclusion, our research indicates the cytotoxic and antimetastatic nature of CP in cells with reduced MMP-9 levels in MCF-7 and MDA-MB-231 breast cancer cell lines." (PMID 34884588, 2021). "A clinical study showed that breast cancer patients subjected to radiotherapy and oral administration of EGCG exhibited reduced activation of MMP-9/MMP-2 accompanied with low serum levels of VEGF and hepatocyte growth factor (HGF)." (PMID 34208196, 2021). "Breast cancer cell lines undergoing CXCL13 stimulation overexpress EMT regulators and MMP9 via the nuclear factor kappa-B ligand (RANKL)-Src pathway, which is critical for breast cancer cell progression and migration." (PMID 34947813, 2021). "The levels of CD147, MMP-2 and MMP-9 transcripts and proteins were significantly increased in BATF-overexpressing breast cancer cells and significantly reduced in BATF-silenced breast cancer cells." (PMID 34096887, 2021). "In breast cancer, MMP2 and MMP9 were determined as important downstream effectors of PI3K/AKT signaling and MMP2 was shown to be activated by PI3K/AKT, regulated by RICTOR for the vasculogenic mimicry of tumor cells." (PMID 35096817, 2021). "Taken together, ORM1 restores the migration ability of breast cancer cells by targeting MMP-2 and MMP-9." (PMID 34654351, 2021). "Zymographic detection of MMP-2 and MMP-9 was observed in breast cancer sera as early as 2004, but it is very likely that the increase attributed to MMP-2 at that time was actually that of the 65 kDa MMP-9." (PMID 35723387, 2021).
breast carcinoma (continued). "According to available literature reports, breast cancer cells of various invasiveness are characterized by variable expression of MMP, e.g., MMP-1, MMP-2, MMP-9, MMP-7, MMP-10, and MMP-19." (PMID 34884588, 2021). "In a human breast cancer cell line (MDA-MB-231) with high metastatic properties, treatment with EGCG resulted in the inhibition of MMP-9 mRNA and protein expression." (PMID 33498927, 2021). "RT-qPCR and western blot results showed that calycosin treatment downregulated the mRNA and protein levels of CD147, MMP-2, and MMP-9 in T47D and MCF-7 breast cancer cells." (PMID 34096887, 2021). "It was suggested that oleuropein inhibits the EMT process in breast cancer cells by inducing upregulation of the epithelial marker E-cadherin, and downregulation of mesenchymal markers MMP-2 and MMP-9." (PMID 34578851, 2021). "Recently, it has been reported that Myr suppresses breast cancer metastasis through the downregulation of the activity of MMP-2 and MMP-9 (MDA-Mb-231Br cells)." (PMID 33498927, 2021). "Our results demonstrated that TGFβ1 treatment increased in vitro migration and invasiveness of breast cancer cells by inducing EMT and increasing the expression of pro-metastatic proteins such as CD147, MMP2, and MMP9." (PMID 34096887, 2021). "Other alterations in MMP-9 and TIMP-1 levels have been observed in subjects with breast cancer compared to controls." (PMID 32392801, 2020). "The present study supported that arctigenin suppressed breast cancer progression through the inhibition of GM-CSF, MMP-3, MMP-9, and TSLP." (PMID 32887217, 2020). "Several studies have revealed that decursin suppresses MMP-9 expression in CT26 colorectal cancer cells, MCF-7 breast cancer cells, and HT1080 fibrosarcoma cells." (PMID 32349276, 2020). "Mechanistically, the overexpression of COX-2 in TAMs activates the AKT pathway in breast cancer cells by releasing IL-6 and PGE2, thereby inducing the expression of MMP-9 and promoting EMT in breast cancer cells." (PMID 33224886, 2020). "This phenomenon has been described in residual primary breast cancer with an increase of VEGF and pro-MMP-9 produced in the surgical field." (PMID 32548671, 2020). "Studies have shown that increased expression of P2 × 7 receptor can increase the expression of MMP-2 and MMP-9 through NF-kB, ERK1/2 and Akt signals, and promote the migration of prostate cancer and breast cancer cells." (PMID 33330466, 2020). "The main component, matrine, can inhibit MMP-9 and MMP-2 activation in highly metastatic human breast cancer MDA-MB-231 cells, reduce the mRNA expression levels of MMP-9 and MMP-2, and finally inhibiting tumor cell invasion." (PMID 33708106, 2020). "Some of them, such as MMP-2, MMP-9 and MMP-14 are overexpressed in breast cancer, inducing collagen degradation and promoting metastasis." (PMID 32984031, 2020). "Intriguingly, ezrin regulates the expression of angiogenic factors in both macrophages as well as tumor cells, as ezrin knockdown in breast cancer cells reduces the macrophage expression of VEGFA and MMP9 mRNAs." (PMID 33086476, 2020). "Contrarily, FOXO3 activation promotes tumor cell invasion through the upregulation of matrix metalloproteinase-9 (MMP-9) and MMP-13 levels in breast cancer cells." (PMID 32629884, 2020). "One of the specificities of breast cancer is that myoepithelial cells act as a protective barrier around the tumor cells and are able to decrease the secretion of MMP-2, MMP-9, and MT1-MMP." (PMID 32984031, 2020). "MMP-2, MMP-9 and MMP-13 are also reported to be overexpressed in breast cancer patients and correlated with more aggressive phenotypes of breast cancer, poor prognosis and decreased life expectancy." (PMID 32586313, 2020).
breast carcinoma (continued). "In agreement with our research, P. japonicum ethanol extract has been found to inhibit invasion by decreasing MMP-9 expression and inhibits PKC/Nf-KB signaling pathway in MCF-7 breast cancer cells[25 ▶]." (PMID 32429645, 2020). "Enhancement of metastatic potency of breast cancer cells by neutrophils was demonstrated by increased MMP‐2 and MMP‐9 mRNA levels, as well as p‐p38 and p‐AKT protein levels only in the contact model." (PMID 32427405, 2020). "In MDA-MB-231 cells was demonstrated that TNF-α increased the expression profile and activity of MMP-9 by inducing JUNB DNA binding activity, thus strengthening the concept of a pro-tumorigenic effect of TNFα in breast cancer." (PMID 33187552, 2020). "MMP-9 was evaluated because it regulates ECM degradation, which, in turn, facilitates breast cancer invasion and migration." (PMID 32473632, 2020). "Daidzein, an isoflavonoid that can be isolated from various plants and herbs, has proven antiproliferative impact on breast cancer cells via inhibiting TNF-α expression, down-regulation of MMP-9 mRNA expression, as evident through RT-PCR analysis." (PMID 33520928, 2020). "To further determine the mechanism of PTTG1-mediated breast cancer cell invasion, we determined the effect of PTTG1 on the regulation of MMP-2 and MMP-9 expression and activity in MDA-MB-231 cells." (PMID 33250768, 2020). "A hypoxic environment in breast cancer can increase the levels of HIF-1α, VE-cadherin, MMP-9, Cdc42, EGFR, p-Akt, and p-mTOR to promote the development of VM via the HIF-1α/VE-cadherin/MMP-9, MMP-2 signaling pathway." (PMID 31993365, 2019). "A clear association between the higher mRNA expression level of ENO1, MMP-2 and MMP-9 with a worse prognosis was already detected, suggesting that the elevated ENO1 and MMPs are promising biomarkers for breast cancer." (PMID 31416219, 2019). "Among which, IBSP, MMP9, TNFAIP6, DHRS3, RIPK4, and CD200 had a diagnose value for patients with breast cancer bone metastasis." (PMID 30918839, 2019). "It implies again remarkable increases in expressions of MMP‐9 and TGF‐β in canine breast cancers, which coincidental well with the tumour malignancy." (PMID 31264317, 2019). "The downregulation of MIEN1 suppressed matrix metallopeptidase 9 (MMP9) expression by downregulating Akt expression, indicating that MIEN1 is a prospective molecular target for breast cancer chemotherapy." (PMID 31581708, 2019). "In breast cancer, KLF8 promotes cell invasion and metastasis by activating the expression of MMP9 in breast cancer cells." (PMID 31624471, 2019). "In cellular models of breast cancer, both MMP-2 and MMP-9, participate in invasion, metastasis and angiogenesis." (PMID 31554180, 2019). "In conclusion, we revealed that Curcumae radix suppresses the level of CCR7 and inhibits migration and metastasis of breast cancer cells to lung, as well as downregulates AP1 and MMP9 expression levels." (PMID 30781353, 2019). "Remarkable strong MMP‐9 and TGF‐β signals were observed in the malignant tissues of canine breast cancers." (PMID 31264317, 2019). "In our study, we detected some published potential biomarker of breast cancer bone metastasis, or their function has been reported in breast cancer bone metastasis such as SPARC, IBSP, MMP9, MMP13." (PMID 30918839, 2019). "In this study, we screened the expressions of MMP‐9 and TGF‐β in the samples of canine breast cancers and confirmed overexpression statues of those two proteins in the malignant tissues." (PMID 31264317, 2019). "Further, we found that knockdown RAI14 inhibits the proliferation, migration and invasion of breast cancer cells by regulating cell cycle and EMT through Akt/Cyclin D1, MMP2, MMP9 and ZEB1/E-cadhrin/Vimentin pathway." (PMID 31772666, 2019). "Here, we investigated the functional relationship, in a cohort of breast cancer patients, between ENO1/MBP-1 expression and MMP-2 and MMP-9 activity levels in both tissues and sera." (PMID 31416219, 2019).
breast carcinoma (continued). "Higher levels of MMP‐9 and MMP‐2 have been repeatedly described in the malignant tissues of the patients with infiltrative breast cancer and lymph node metastasis." (PMID 31264317, 2019). "Consistent with this, we found that, in breast cancer cells, both MMP13 and MMP9 were upregulated by Osx, suggesting that Osx has a function in invasion, an initial stage in the metastasis cascade." (PMID 30631043, 2019). "LPA induces the expression of MMP-2 or MMP-9 in a variety types of cancer cells 32-35, which motivated us to investigate the effect of LPP1 on MMPs in breast cancer cells." (PMID 31534541, 2019). "Previous studies confirmed that the gene-transfected MMPs breast cancer cell line MDA-MB-436 was inoculated into nude mice and induced the over production of MMP-2 and MMP-9." (PMID 31514467, 2019). "The experiments further demonstrated that SPG-56 inhibited the metastasis of breast cancer in MCF-7 and 4T1-bearing mice by altering the expression of MMP2, MMP9, VEGF, Occludin and Claudin." (PMID 30651572, 2019). "MMP9 and MMP13 is up-regulated in breast cancer tissue, and were involved in bone metastasis of tumor progression." (PMID 30918839, 2019). "The upregulation of CD147 in MDA-MB-435 breast cancer cells promoted tumor growth, infiltration and metastasis in nude mice, and the expression of MMP-2 and MMP-9 increased in tumor cells." (PMID 31196010, 2019). "In the breast cancer cell line MDA‐MB‐231, the decrease of mtROS induced by HIC‐5 resulted in destabilization of the gelatin matrix metalloprotease MMP9." (PMID 30680933, 2019). "In human breast cancer, KLF8 promotes the invasion and metastasis of cancer cells by promoting the expression of matrix metalloproteinase 9 (MMP9)." (PMID 31624471, 2019). "In summary, more aggressive expressions of MMP‐9 and TGF‐β were detected in the malignant canine breast cancers." (PMID 31264317, 2019). "MMP‐9 and TGF‐β expressions in breast carcinoma and adenoma were evaluated by the individual immunohistochemical (IHC) assays." (PMID 31264317, 2019). "Immunohistochemical analysis was performed using tissue samples of fibroadenoma and breast cancer to assess MMP-2 and MMP-9 antigen expression." (PMID 31839881, 2019). "By downregulating MMP9, MMP13, VEGF, IL-8, and PTHrP, knockdown of Osx inhibited invasion of breast cancer cells and osteolytic metastasis; overexpression of Osx had the opposite effect." (PMID 30631043, 2019). "In breast cancer cells, TPX2 promotes cancer cell invasion and migration via regulating MMP2 and MMP9 expression." (PMID 31285741, 2019). "The relationships of MMP-2 and MMP-9 to the degradation of the ECM and tumor metastasis are significant; thus, they are regarded as progression markers in breast cancer." (PMID 31783821, 2019). "In this study, we have confirmed again markedly increased expressions of MMP‐9 and TGF‐β in the malignant tissues of 34 canine breast carcinomas." (PMID 31264317, 2019). "The distributions of MMP‐9 and TGF‐β in the tissues of canine breast cancers were screened by immunohistochemical assays." (PMID 31264317, 2019). "In the study of breast cancer cell line MCF-7, it was found that SM extract reduced the ability of metastasis and invasion of cancer cells by inhibiting the expression of MMP-9 mediated by MAPK/ap-1 signal transduction pathway." (PMID 31636686, 2019). "We also demonstrated that inhibition of the activity of either MMP‐9 or TGF‐β sufficiently blocked the MMP‐9 overexpression induced the activation of SMAD signalling and enhancement on invasion in the breast cancer cell lines." (PMID 31264317, 2019).
breast carcinoma (continued). "Targeting and knockdown of TAK1 inhibits chemokine receptor 7, MMP-9, IL-8, COX-2, tumor growth and metastasis of breast cancer." (PMID 31831717, 2019). "We also demonstrated that the inhibitors specific for MMP‐9 and TGF‐β sufficiently blocked the overexpressing MMP‐9 induced the activation of SMAD signalling and enhancement on invasion in the tested breast cancer cell lines." (PMID 31264317, 2019). "The majority of the breast cancer tissues were positive for the lytic activities corresponding to the latent and activated form of MMP-2 and MMP-9." (PMID 31416219, 2019). "Previous studies have shown that MRE11 overexpression in breast cancer cells leads to cell proliferation by stimulating STAT3 signalling and enhances migration and invasion capabilities through activation of MMP-2 and MMP-9." (PMID 31221177, 2019). "In particular, miR-21, MMP1, MMP9, MMP13, CXCR4 and vimentin were found overexpressed in the invasive margins of breast cancer tissues of clinical samples and in the cancer cell lines; E-Cadherin, on the other hand, was decreased." (PMID 31362429, 2019). "Gene MMP-9 and VEGFA play a critical and dual role in cancer metastasis and angiogenesis to foster progression of breast cancer cells in vitro." (PMID 30728391, 2019). "The expressions of BMAL1 and MMP9 were also examined in different human breast cancer cell lines, showing that the expression of BMAL1 was higher in more invasive breast cancer cells and was positively correlated with the expression of MMP9." (PMID 31346317, 2019). "Blocking the binding of TGF‐β to its receptor by special inhibitor attenuates MMP‐9‐induced phosphorylation of SMAD2/3 and the increases in SMADs in the breast cancer cells." (PMID 31264317, 2019). "CTSG is also capable of activating pro-MMP-9, that cleaves and releases active transforming growth factor-β (TGFβ), MMP-13 and RANKL at the tumor-bone interface of mammary tumor-induced osteolytic lesions." (PMID 31647805, 2019). "Further analysis of the METABRIC dataset revealed an increase in IL-6, CCL2, and MMP-9 expression in patients with low IGF-1R, consistent with our mouse tumor model and data in human breast cancer cell lines." (PMID 30458886, 2018). "Other research investigated multiple biomarkers in metastatic breast cancer patients, including serum neuron-specific enolase (NSE) level, serum MMP-9 level, and serum HER2 extracellular domain level (ECD)." (PMID 30262739, 2018). "The potentially important role of matrix-degrading enzymes in breast cancer has been stated for many years, in particular in relation to the activities of MMP-2 and MMP-9." (PMID 30060564, 2018). "HGF is believed to act as an initiation signal for the onset of EMT, which results in the upregulation of effector molecules, such as MMP-2 and MMP-9, and activation of STAT-3 to aid EMT and the metastatic dissemination of breast cancer cells." (PMID 30314527, 2018). "The process of migration and invasion are an important step in the metastasis of breast cancer, and these processes can be regulated by a variety of factors such as BRMS1, E-cadherin, CXCL12, MMP9, Orai1, Stim1, TGF-β, and VEGF." (PMID 29316690, 2018). "Using breast cancer cell lines, McLaughlin and coworkers reported that NEDD9 depletion reduced MMP2 and MMP9, cell invasion and matrix degradation." (PMID 29876004, 2018). "Formononetin can also inhibit the migration and invasion of breast cancer cells by suppressing MMP2 and MMP9 through phosphoinositide 3-kinase/protein kinase B (PI3K–Akt) signaling pathways." (PMID 30092799, 2018). "ER is amongst the most important biomarkers for breast cancer; thus, all three TAM biomarkers (CD68, CD163, and MMP-9) are examined in the context of ER status." (PMID 30558648, 2018). "Here, we provide further evidence that ALT-C binding to α2β1 integrin decreases MMP-9 and MMP-2 content in human breast cancer cells and decreases MMP-2 content in human microvascular endothelial cells (HMEC-1) by zymography." (PMID 29713337, 2018).